IL6 (interleukin 6)
Diseases named in the same sentence as IL6 in open-access papers (continued):
Sharing a sentence is not in itself a finding about the gene and the disease.
gynecological cancer (7 papers, 2017 to 2025). "Vaginal Lactobacillus may protect from gynecological cancers by inhibiting pro-inflammatory bacteria, such as those implicated in pelvic inflammatory disease, and by reducing inflammatory cytokines IL-1β and IL-6." (PMID 34178459, 2021). "It was found that the IL-6 level in 28.5% of patients with no ovary conditions and 6.7% with benign conditions was below the detection limit of the measurement method used." (PMID 34572929, 2021). "The levels of IL-6 in blood serum and ascites were determined and compared with those of a group of 12 obese women aged 38 to 73 years with benign ovary conditions and a group of 21 obese women aged 40 to 84 years without ovary conditions." (PMID 34572929, 2021).
hantavirus infection (7 papers, 2011 to 2025). "As the hallmark in hantavirus infections is the capillary leakage caused by endothelial dysfunction, it is of interest that IL-6 has been shown to cause endothelial barrier dysfunction via the protein kinase C pathway." (PMID 35062248, 2021). "This is an interesting finding as IL6 and other cytokines upregulated in human hantavirus infections (i." (PMID 34339406, 2021). "Overall, IL-6 appears as a useful biomarker when assessing the severity of PUUV hantavirus infection." (PMID 35062248, 2021). "To further analyze the relation of pro- and anti-inflammatory cytokines during the course of disease in acute hantavirus infection, we compared expression of IL-2, IL-5, IL-6." (PMID 22085404, 2011). "The early phase of acute hantavirus infection (average 6 days after onset of symptoms) was characterized by significant elevation of cytokine expression of IL-2, IL-6, IL-8, TGF-β1 and TNF-α versus healthy controls." (PMID 22085404, 2011). "Acute hantavirus infection was characterized by significantly elevated levels of IL-2, IL-6, IL-8, TGF-β1 and TNF-α in both early and late phase compared to healthy controls." (PMID 22085404, 2011). "Differences in IL-6 were observed between human hantavirus infections and the hamster models." (PMID 34339406, 2021). "One study investigating the role of serum biomarkers in hantavirus infection and disease severity showed intestinal fatty acid binding protein (I-FABP) and interleukin 6 (IL-6) cytokine levels were associated with disease severity and poor outcome among Argentine HPS patients." (PMID 31505806, 2019). "Cytokine expression of IL-2, IL-5, IL-6, IL-8, IL-10, IFN-γ, TNF-α and TGF-β1 was analysed by ELISA during the early and late phase of acute hantavirus infection (average 6 and 12 days after onset of symptoms, respectively)." (PMID 22085404, 2011). "Significantly elevated serum levels of IL-2, IL-6, IL-8, TGF-β1 and TNF-α were also observed when the late phase of acute disease was compared with healthy controls, demonstrating a profound and prolonged pro-inflammatory response to hantavirus infection." (PMID 22085404, 2011).
IgG4-related disease (7 papers, 2016 to 2024). "Some patients with IgG4-related disease (IgG4-RD) exhibit elevated serum interleukin (IL)-6 with excessive inflammatory reactions or with repeating relapse." (PMID 31951598, 2020).
intestinal obstruction (7 papers, 2016 to 2024). Blockage of the normal flow of the intestinal contents within the bowel. "Clinically, significant correlations between elevated serum IL-6 levels and other clinical factors such as serum CEA, CRP, and bowel obstruction have been previously reported." (PMID 26858756, 2016).
invasive carcinoma (7 papers, 2014 to 2025). A carcinoma that is not confined to the epithelium, and has spread to the surrounding stroma. "The exact role of IL-6 in the early stages of oral carcinogenesis, before invasive carcinoma is formed, needs further investigation." (PMID 26595830, 2016). "Notably, PSC-derived IL-6 directly enhanced STAT3-dependent progression of PanINs towards invasive carcinomas." (PMID 32865617, 2020). "Other differentially expressed transcripts include S100A7, LCN2, CXCL14, and CD207 (decreasing expression from premalignant lesions to invasive carcinoma), as well as IDO1, IL6, IL8, THBS1, and FN1 (increasing expression from premalignant lesions to invasive carcinoma)." (PMID 38706595, 2024). "Previously collected plasma samples from patients with benign breast disease, in situ carcinoma, invasive carcinoma with no lymph node involvement (Inv/LN−), and invasive carcinoma with lymph node involvement (Inv/LN+) were evaluated by ELISA for CMV IgG, cmvIL-10, and human cIL-10, IL-6, and TNFα." (PMID 39172306, 2024).
invasive ductal carcinoma (7 papers, 2004 to 2024). "It has previously been shown that there is a correlation of VEGF expression with IL-6 and its receptors in tumor cells, which is associated with poor survival of individuals with HER2-invasive ductal carcinoma." (PMID 34206393, 2021). "To assess the relevance of tumor tissue expression of OSM and IL-6 in the context of invasive ductal carcinoma (IDC) patient survival, we used the Curtis Breast dataset obtained from OncomineTM." (PMID 31007849, 2019). "In this study we compared the gene and protein expression of ERα and ERβ, PR, IL-6 and IL-8 in cells isolated from invasive ductal carcinomas and benign breast tissue specimens." (PMID 25269750, 2014). "The levels of IL-6 mRNA and protein are strongly reduced in invasive ductal carcinomas, suggesting an inverse relationship between tumour aggressiveness and the expression of this cytokine." (PMID 14735187, 2004). "In relation with this last comment, in previous studies conducted in our laboratory, we have observed that tumor cells of BCPs (invasive ductal carcinoma, stage I/II) produce bone marrow-MSCs chemotactic substances, such as IL-6, SDF-1, and CCL-2, among others." (PMID 37719885, 2023). "Data presented here are innovative and expand the field in that we measured gene and protein expression of ERα and ERβ, PR IL-6 and IL-8 in uncultured CD49f/CD24 BCSCs from individual human invasive ductal carcinomas." (PMID 25269750, 2014).
iron metabolism disorders (7 papers, 2020 to 2025). "CIHH improves iron metabolism disorder in obese rats possibly through the down-regulation of hepcidin by decreasing IL-6 and increasing Epo." (PMID 33292270, 2020). "Moreover, Lf’s ability in counteracting and reverting iron disorders, by modulating immune response and down-regulating pro-inflammatory cytokines, such as IL-6, has been demonstrated both in in vitro and in vivo models, as well as in clinical trials." (PMID 32664543, 2020). "No detectable levels of IL-1β and IL-6, the main cytokines involved in iron disorders, were recorded both in basal and Spike/bLf-stimulated conditions (data not shown)." (PMID 36297546, 2022).
ischemia reperfusion injury (7 papers, 2009 to 2024). Adverse functional, metabolic, or structural changes in ischemic tissues resulting from the restoration of blood flow to the tissue (reperfusion), including swelling; hemorrhage; necrosis; and damage from free radicals. "Several other cardiomyocyte-associated genes linked with ischemia-reperfusion injury (IRI), inflammation and cardiac distress were downregulated through IL-6 blockade 43–51." (PMID 38830846, 2024). "High-mobility group box 1 has been nominated to be an early mediator of inflammation and organ damage in ischemia-reperfusion injury by increasing production of tumor necrosis factor-α, IL-1, IL-6, and other pro-inflammatory mediators." (PMID 35395776, 2022). "In a pre-clinical model of ischemia-reperfusion injury, prazosin administration resulted in decreased expression of IL-6, TNF-α, IL-10, and IL-1, and prevented mortality." (PMID 33869251, 2021). "In a mouse ischemia-reperfusion injury (IRI) model, this peptide, GV1001 efficiently inhibited the production of IL-6 and MCP-1, which are associated with a decrease in the infiltration of neutrophils and macrophages in the kidney after IRI." (PMID 27655706, 2016).
ischemic disease (7 papers, 2018 to 2026). Lack of blood supply to an area of the body, resulting in impairment of tissue oxygenation. "Previous research reported enhanced expression of IL-1 β and IL-6 in autoimmune and ischemic diseases." (PMID 34680549, 2021). "In addition, BA can alleviate oxygen-glucose-deprived challenged microglia injury in ischemic diseases by attenuating expression of inflammatory cytokines TNF-α, IL-1β, IL-6, and IL-8 through TLR4 pathway." (PMID 36408278, 2022).
Japanese encephalitis (7 papers, 2010 to 2023). A disease due to a virus transmitted by an arthropod). "Elevated levels of IL-6 have been measured in clinical samples from patients that developed a more severe form of Japanese encephalitis." (PMID 37261350, 2023). "Another study reported that BCG vaccine injection downregulated the expression of IL-6 in a Japanese encephalitis mice model." (PMID 38002349, 2023). "Similarly, IFNs and proinflammatory cytokines including TNF-α and IL-6 were elevated in patients with acute Japanese encephalitis." (PMID 30016363, 2018). "In the case of ZO-1, Japanese encephalitis viral infected astrocytes induce the expression of VEGF, IL-6, and MMP2/MMP-9 that upregulate the expression of the E3-Ub-ligase component n-recognin-1 that triggers ZO-1 ubiquitination and degradation." (PMID 36291162, 2022). "Microglial activation and release of inflammatory cytokines such as IL-6, IFN-γ and TNF-α can affect the differentiation and proliferation of neuroblasts in SVZ, as shown in a murine model of Japanese encephalitis." (PMID 28448579, 2017).
Nasal congestion (7 papers, 2022 to 2026). Reduced ability to pass air through the nasal cavity often leading to mouth breathing. "Taking into account the analyzed variables, only patients with nasal congestion showed significantly higher IL-6 levels (28.2 pg/mL ± 39.0 pg/mL vs. 12.0 pg/mL ± 8.1 pg/mL; p = 0.013)." (PMID 40647649, 2025). "Additionally, IL-6 levels in saliva were elevated in patients with nasal congestion and in those with 11 or more symptoms in the Self-RPD+ group." (PMID 40647649, 2025). "IL-6 in nasal secretions was positively correlated with nasal obstruction (r = 0.3516, P = 0.0261)." (PMID 39525400, 2024). "Nasal obstruction VAS score, peripheral blood Eos %, peripheral blood Neu %, serum sIgE, serum IL-6 and peripheral blood Treg were continuous variables, and the assignment was included in the actual value." (PMID 39139176, 2024).
ocular hypertension (7 papers, 2016 to 2025). Abnormally high intraocular pressure. "Stattic administration (5 mg/kg, intraperitoneal, once a day for 7 days) fully attenuated the production of IL-1β and IL-6 in ocular hypertensive animals." (PMID 33628191, 2021). "Stattic, a selective STAT3 inhibitor, administration resulted in a complete attenuation in the production of IL-1β and IL-6 in ocular hypertensive animals." (PMID 33628191, 2021). "Data illustrated an increase in the leukemia inhibitory factor (LIF) and IL-6 in ocular hypertensive animals." (PMID 33628191, 2021). "Additionally, animal studies using the microbead occlusion model of ocular hypertension have shown that IL-6 plays a significant role in RGC axon degeneration and in IOP-dependent visual acuity deterioration." (PMID 34069173, 2021). "Furthermore, we have shown that elevated protein expression of TNF-α, IL-1β, and IL-6 were attenuated by SNC-121 treatment in ocular hypertensive animals." (PMID 33628191, 2021). "Preclinical studies in Gerbil indicated that ES reduced microglia activation and density and decreased the expression of Interleukin 6 (IL-6) and COX-2 in the acute ocular hypertensive injury model." (PMID 36158207, 2022). "The mRNA expression of IL-1β, TNF-α, Fas, IL-6, leukemia inhibitory factor, and IFN-γ was increased significantly in the retina of ocular hypertensive animals at day 7, post injury." (PMID 33628191, 2021). "In the current study, we have also shown that protein expression of IL-1β and IL-6 was remarkably increased in RGC and nerve fiber layers in ocular hypertensive animals, which was completely inhibited in SNC-121 treated ocular hypertensive animals." (PMID 33628191, 2021).
Onset (7 papers, 2012 to 2025). The age group in which disease manifestations appear. "It has also been shown that increased levels of cytokines such as IL-2, IL-6, IL-8, TNF-α in subjects with new-onset AF, can stimulate mesothelial cells to produce CA125." (PMID 31058877, 2019).
oral cavity cancer (7 papers, 1993 to 2025). A primary or metastatic malignant neoplasm involving the oral cavity. "Nakano and collaborators (1999) identified elevated concentrations of pro-inflammatory cytokines TNF and IL-6 in tumor tissues of oral cavity cancer patients." (PMID 40733296, 2025). "Subsequent studies have identified higher concentrations of TNF and interleukins (IL-6 and IL-8) in patients with oral cavity cancer." (PMID 40733296, 2025). "Since patients are commonly diagnosed with oral cavity carcinoma at the later stages of the disease, it is expected that serum IL-6 levels increase with cancer stage." (PMID 26082902, 2015). "Despite the controversies, IL-6 is suggested as a biomarker for early diagnosis and follow-up to detect relapse in oral cavity carcinomas." (PMID 26082902, 2015). "IL-6 may, e.g. act as an autocrine or paracrine tumor growth factor, but also as an anti-apoptotic agent on cancer cells, as is suggested to be the case in oral cavity cancer." (PMID 26079381, 2015). "We studied the production of interleukin 1 beta (IL-1 beta) and interleukin 6 (IL-6) by peripheral blood monocytes from 22 patients with HNSC (12 larynx and ten oral cavity cancers) in comparison with monocyte cytokine production of age-matched healthy subjects." (PMID 8353036, 1993).
ovarian clear cell cancer (7 papers, 2016 to 2024). An invasive malignant neoplasm that arises from the ovary and is characterized by a predominance of clear and hobnail malignant epithelial cells. "Ovarian clear cell carcinoma (OCCC) is a subtype of epithelial ovarian cancer (EOC) that is associated with elevated interleukin-6 (IL-6) expression, resistance to chemotherapy, and increased mortality." (PMID 33833265, 2021). "Another study of Toshiyuki Seki etc. highlighted the role of interleukin 6 as an enhancer of anti-angiogenic therapy for ovarian clear cell carcinoma, as IL-6 induced VEGF production by tumor cells and consequently activated angiogenesis." (PMID 38893732, 2024). "The upregulation of IL-6, STAT3, HIF-1α observed in ovarian clear cell cancer samples indicates an IL-6/STAT3/HIF1α/VEGF autocrine activation loop in EOC thereby facilitating tumor angiogenesis." (PMID 35401182, 2022). "Furthermore, IL-6 autocrine signaling was reported in an ovarian clear cell carcinoma study that IL-6 could regulate SPINK1 expression." (PMID 33916984, 2021). "Studies have shown that targeting the autocrine IL-6 (interleukin-6)-SPINK1 (serine peptidase inhibitor Kazal type) signal axis can inhibit the metastasis and spread of ovarian clear cell carcinoma, which provides a possibility while replicating the therapy." (PMID 35310909, 2022).
Ovarian cyst (7 papers, 2013 to 2024). The presence of one or more cysts of the ovary. "Enzyme-linked immunosorbent assay (ELISA) of ovarian cyst fluids have indicated that the cytokines interleukin-6 (IL-6) and IL-10 exist at higher levels in patients with a more advanced stage of disease." (PMID 26769844, 2016). "The elevated interleukin-6 may cause ovarian cyst formation and poor fertility in cows." (PMID 39684341, 2024). "Furthermore, an in vitro study from endometrial stromal cells isolated from chocolate ovarian cysts showed a significant ability to produce IL-6 with production comparable to that of peritoneal macrophages." (PMID 24453419, 2013). "denoted an increased expression of IL-6 and TNF-α in the fluid of cystic ovaries in the untreated group, providing this may be related to the presence of follicular cysts." (PMID 39495423, 2024). "In the present study, we found that TNF, IL6, and IL1B were all involved in the NOD-like receptor signaling pathway, which may provide a new field for Jingshu granules in the treatment of ovarian cysts." (PMID 33623786, 2021).
pancreatic diseases (7 papers, 2017 to 2024). "IL-6 was reported to be elevated in alcohol-addicted patients with alcohol-induced liver and/or pancreatic diseases, and the association between immune mediators and psychiatric comorbidity was noticed in those patients." (PMID 38275640, 2023). "In view of the finding that IL-6 is highly accurate for the prediction of SAP, our pancreatic disease center routinely detected IL-6 in patients with AP admitted in the early stage and recorded it in the AP database since September 2018." (PMID 36467730, 2022).
parasite (7 papers, 2014 to 2025). "Interestingly, our research suggests that IL-6, a cytokine less commonly associated with parasite infections, may play a significant role in the immune response." (PMID 40918106, 2025). "For PRU infection, IL-6 and IL-8 synthesis increased significantly between 8 h to 24 h post infection, whereas the parasite burden reached a peak significantly at 14 h and then decreased sharply until 48 h." (PMID 24886982, 2014). "Our analysis shows that measuring a combination of host parameters (e.g. Syndecan-1, IL-6, platelet levels) and total parasite biomass (PvLDH) could predict the extent of parasite infection outside of circulation." (PMID 34585667, 2021).
pressure ulcers (7 papers, 2015 to 2025). "In stage 1 pressure ulcers on the sacrum, IL-1β, IL-6, IL-8, TNF-α and IFN-γ were found to be upregulated." (PMID 39772735, 2025). "At day 6 post‐I/R, H2 treatment significantly reduced the relative mRNA and protein expression of TNF‐α, IL‐1β, IL‐6 and IL‐8 in wounded tissue, and their expression was lowest in pressure ulcer mice treated with 75% H2." (PMID 29921037, 2018). "Besides, vessel formation and wound healing were enhanced in hESC-MSC-Fb-treated skin tissues compared to PBS- or hESC-MSC-treated skin tissues, along with decreased IL-6 expression at 4 days after the formation of pressure ulcer wound in a mouse model." (PMID 30693037, 2018). "Therefore, we surmised that treatment with hESC-MSC-Fbs attenuated IL-6 expression in the early inflammatory response after the induction of pressure ulcers, leading to scarless wound healing." (PMID 30693037, 2018). "IL-1β and IL-6 were increased in preference of other cytokines, which may indicate a superior role of IL-1β and IL-6 in the formation of pressure ulcers." (PMID 26177082, 2015). "Prolonged up-regulation of IL-1β, and IL-6 might enhance local inflammation, and continuous local inflammation may contribute to the pressure ulcer formation." (PMID 26177082, 2015). "The concentrations of IL-1β, IL-6, and TGF-β in blood and wounds were all significantly elevated in response to pressure ulcers while the activation of KLF4 significantly suppressed the expression of these cytokines." (PMID 34568499, 2021). "Hypoxic conditions in pressure ulcers result in increased cell death and release of toxic metabolites such as cyclooxygenase (COX)-2 and interleukin (IL)-6 through upregulation of extracellular signal-regulated kinase (Erk) and p38 mitogen-activated protein kinase (MAPK)." (PMID 33374656, 2020). "In diabetic wounds, elevations in IL-6 and TNFα further lowers dermal fibroblast proliferation through downregulation of PI3K/AKT activity, resulting in impaired collagen deposition and wound contracture, although this interaction is not fully elucidated in pressure ulcer pathophysiology." (PMID 33374656, 2020).